GAS5 (growth arrest specific 5)
Diseases named in the same sentence as GAS5 in open-access papers (continued):
Sharing a sentence is not in itself a finding about the gene and the disease.
cancer (continued). "In recent findings, some lncRNAs, such as actin filament associated protein 1 antisense RNA1 (AFAP1-AS1), HOX transcript antisense RNA (HOTAIR), growth-arrest-specific transcript 5 (GAS5), have been reported to regulate cancer metastasis process by multiple ways." (PMID 28039470, 2017). "Several investigations on large clinical cancer samples have demonstrated that specific lncRNAs, such as HOX transcript antisense RNA (HOTAIR) and Growth arrest specific 5 (GAS5), can influence the outcomes of radiotherapy and act as valuable prognostic biomarkers." (PMID 28872613, 2017). "Thus in cancers with deficient GAS5 expression, the GAS5 HREM oligonucleotide may have therapeutic potential, not only by acting as an apoptotic inducer per se, but also by restoring the effectiveness of more conventional oncotherapies on therapy-resistant cancer cells." (PMID 26862727, 2016). "Consistent with this hypothesis, several lncRNAs, such asPTENP1, HULC, GAS5, loc285194,HOTAIR as well as HOTTIP, have been identified as miRNA targets in various cancers, which provide further layers of understanding lncRNA regulation during carcinogenesis." (PMID 26710269, 2015). "For example, LincRNA-p21\GAS5\MALAT1, which are located in the cytoplasm and act as competing endogenous (ceRNAs) or interact with RBPs, could enhance mRNA stabilization and translation in the context of cancer progression." (PMID 38041756, 2024). "Exosomal lncRNA like MALAT1, growth arrest-specific 5 (GAS5), H19, HOTAIR, small ubiquitin-like modifier 1 SUMO1 pseudogene 3 (SUMO1P3) and X-inactive specific transcript (XIST) were previously shown upregulated in the blood, lung and breast tissues of cancer patients." (PMID 37153158, 2023). "Accordingly, some cell functions of GAS5 were not investigated in cancer cells." (PMID 36230902, 2022). "Indeed, GAS5 (Growth Arrest Specific 5) directly binds to HuR and promotes its cytoplasmic translocation, thereby stabilizing the FAM83B (Family With Sequence Similarity 83 Member B) transcript and promoting cancer cell proliferation, migration, and invasion." (PMID 35884580, 2022). "However, the overexpression of LncRNA GAS5 decreased miR-544 expression, by increasing runt related transcription factor 3 (RUNX3) expression, favouring increased activated NK cell-mediated cytotoxicity suggesting a potential therapeutic target for cancer." (PMID 34303380, 2021). "As emerging stars in cancer biomarkers, more and more lncRNAs were identified, and some functioned as oncogenes, such as CCAT2, HOTTIP and TUG1, while some may be acted as tumor suppressor genes, such as MEG3, GAS5, ANRIL." (PMID 28977885, 2017). "In the current study, we identified 24 differentially expressed lncRNAs in NPC including GAS5, NEAT1 and H19, which contribute to the development and progression of cancers and might serve as novel, non-invasive biomarkers for cancer diagnosis, progression and prognosis." (PMID 26246469, 2015). "However, the underlying molecular mechanisms remain unknown, and the expression of GAS5 after the treatment with anti-cancer agent in BC cells has not been investigated." (PMID 29445179, 2018). "The regulation relationships between GAS5 and UL3 in diseases have not been reported, but the roles of UL3 have been emphasised in previous studies, mainly in several cancers." (PMID 38812041, 2024). "ZFAS1 and GAS5, but not SNHG5 and SNHG8 were significantly upregulated in cancer tissues in HCC patients." (PMID 34072570, 2021). "In vivo, a significant negative correlation is also observed between the GAS5 levels and the CDK6 levels in cancer tissues (r2 = 0.168, p = 0.013)." (PMID 24069260, 2013).
cardiovascular diseases (10 papers, 2021 to 2025). "In inflammatory-associated diseases, the effects of GAS5 can typically be defined as having a context-dependent relationship, as described for cardiovascular diseases." (PMID 39941145, 2025). "GAS5 can widely regulate the progression of different diseases, including cardiovascular diseases, through various mechanisms." (PMID 40563948, 2025). "Beyond miR-21, GAS5 has been shown to exacerbate various cardiovascular diseases by modulating other miRNAs and their downstream signaling pathways, with studies highlighting the therapeutic potential of GAS5 knockdown or knockout strategies." (PMID 39941145, 2025). "Future research should aim to clarify GAS5’s mechanisms across a myriad of cardiovascular disease models to advance novel treatments within this field." (PMID 39941145, 2025). "The role of GAS5 in cardiovascular disease highlights its complex and context-dependent interplay with miRNA and downstream pathways." (PMID 39941145, 2025). "The regulatory mechanisms of GAS5 involved in the pathophysiological process of cardiovascular diseases are very complex, and one of them is to regulate various microRNAs and their downstream target genes." (PMID 38561456, 2024). "The role of GAS5 in cardiovascular diseases reveals a more nuanced relationship." (PMID 39941145, 2025). "Emerging evidence indicates that GAS5 exhibits pleiotropic roles across diverse biological contexts and disease pathologies, including carcinogenesis, autoimmune disorders, metabolic syndromes, and notably, cardiovascular diseases." (PMID 40563948, 2025). "Similarly, many genes, including CALM2, PDCD4, TXNIP, CYP11B2, P2Y12, and ROCK1, have been identified as downstream targets of GAS5 in cardiovascular diseases." (PMID 38812041, 2024). "GAS5 is a lncRNA that is involved in the development of cardiovascular disease." (PMID 35619068, 2022). "In addition, GAS5 has also been reported to serve as a ceRNA in cardiovascular diseases and inhibit the negative regulation of miRNAs on downstream gene expression." (PMID 34698362, 2021). "The lncRNA GAS5 plays an important role in a variety of cardiovascular diseases." (PMID 34698362, 2021).
infection (10 papers, 2019 to 2025). The state of being infected such as from the introduction of a foreign agent such as serum, vaccine, antigenic substance or organism. "Expression analysis revealed different profiles between 8 h and 24 h post-infection, also showing an increase in the diversity of differentially expressed splice variants at 24h post-infection, as observed with the expression of Gas5." (PMID 38464511, 2024). "More specifically, during early infection (12 to 24 hpi), the Gas5/Gel1-like gene, which encodes a GH72 1,3-β-glucanosyltransferase with sequence similarity to Gas5 enzymes from yeast and Gel1 from Aspergillus spp." (PMID 37039647, 2023). "On the other hand, the LV-GAS5 infection in SCs significantly increased the expression of GAS5, while the level of miR-21 was downregulated." (PMID 37672149, 2024). "This study focuses on characterize the expression profile of LincRNA-cox2, Lethe, lincRNA-EPS, Malat1 and Gas5 during infection of macrophages by B. abortus." (PMID 38464511, 2024). "A noticeable exception was represented by GAS5 and GADD45b, whose expression levels increased overtime, pointing to growing cell stress during the course of infection, likely initiating cell apoptosis at the later time point of this analysis." (PMID 36768954, 2023). "GAS5 is upregulated after infection, and GAS5 5′ end binds viral protein NS3 and blocks NS3 function." (PMID 32214045, 2020). "Then our focus shifted to the downstream mechanism of lncRNA GAS5 involving in the protective effect of CGA against ST infection." (PMID 33240872, 2020). "To confirm that GAS5 played a protective role against ST infection through competitive binding, we performed cell rescue experiments." (PMID 33240872, 2020). "NORAD, THRIL, and GAS5 are involved in regulation of the NF-κB signaling pathway, a central axis of immune activation in response to respiratory viral infections and showed increased expression in infection." (PMID 41267684, 2025). "Hence, we used qPCR to evaluate the expression of lincRNA-Cox2, Lethe, lincRNA-EPS, Malat1, and Gas5 during the first 12 h of infection in RAW 264.7 cells." (PMID 38464511, 2024). "Considering the differences observed in the expression profile of the analyzed lncRNAs in B. abortus-infected RAW264.7 macrophages at 8 and 24 h post-infection, we examined the expression levels of lincRNA-Cox2, Lethe, lincRNA-EPS, GAS5, and Malat1 by RT-qPCR after 1, 6, and 12 h post-infection." (PMID 38464511, 2024). "Our research indicated that the GAS5/YY1/STX17 pathway may represent a new regulatory network that controls the disruption of autophagy in response to infection by Acinetobacter baumannii." (PMID 34304694, 2021). "But the sole or combined roles of CGA and lncRNA GAS5 in ST infection are incompletely understood." (PMID 33240872, 2020). "On the other hand, at 24 h post-infection, three splicing variants of the Ptgs2os2 gene (ENSMUST00000241778.1, ENSMUST00000245671.1, and ENSMUST00000241512.1), one of the Malat1 gene (ENSMUST00000249653.1), and one of the Gas5 gene (ENSMUST00000159037.3) were overexpressed in infected RAW264.7." (PMID 38464511, 2024). "The expressions of lncRNAs UCA1, GAS5, NORAD, BISPR, and NEAT1 were quantified using Illumina cDNA (RNA-seq) sequencing data and compared to dRNA-seq using fold change expression in infection (normalized reads in infected/normalized reads in uninfected)." (PMID 41267684, 2025). "Especially, several lncRNAs that exhibited transcriptional regulation, such as GAS5, THRIL, MIR155HG, and UCA1, also displayed consistent or increased m6A methylation signals following infection." (PMID 41267684, 2025). "Our analysis shows increased m6A methylation of GAS5, NORAD, and UCA1 during infection, pointing to further layers of post-transcriptional regulation." (PMID 41267684, 2025).
infection (continued). "Our results demonstrate that infection of macrophages with Brucella abortus, induces significant changes in the expression of LincRNA-Cox2, Lethe, LincRNA-EPS, Gas5, and Malat1." (PMID 38464511, 2024). "Knowing the global expression of lncRNA in B. abortus-infected BMM at 24 h, we proceeded to study the specific expression of five lncRNA: lincRNA-Cox2, lincRNA-EPS, Lethe, Malat1, and Gas5 in the RAW264.7 cell line at 8 and 24 h post-infection." (PMID 38464511, 2024). "Following transfection/infection of SCs in vitro, the CCK-8 assay and Transwell assay revealed that silencing of GAS5 significantly promoted the proliferation and migration of SCs compared to the overexpression of GAS5." (PMID 37672149, 2024). "Our transcriptomic analysis shows that in response to infection, there are changes in the expression profile of lincRNA-Cox2, Lethe, lincRNA-EPS, Gas5 and Malat1." (PMID 38464511, 2024). "In this light, increased GAS5, TBL2, ATF4, and DDIT3 would be explained as related to cell stress upon infection." (PMID 36768954, 2023). "We found that GAS5 and TBL2 were significantly upregulated, respectively, at 9 and 3 h post-infection compared to the previous time points." (PMID 36768954, 2023). "Other lncRNAs (i.e., BANCR, GAS5, GSTT1-AS1, PVT1, RMRP, and SNHG15) increased at one or more time-points during infection; BANCR was highly increased in infected cells, but only at 24 h." (PMID 31547203, 2019). "Moreover, the functions and mechanisms involving cross-talk between GAS5 and YY1 in the induction of autophagy by infection with Acinetobacter baumannii have yet to be elucidated." (PMID 34304694, 2021). "Hence, we focused on lncRNA GAS5 and tried to figure out the regulatory mechanism of CGA in the treatment of ST infections." (PMID 33240872, 2020). "In several transcripts, such as GAS5, LINC00278, and LINC01619, we observed an increased frequency of adenine (A) and uracil (U) residues surrounding the DRACH motif in infected cells, suggesting a possible shift in sequence preference for m6A deposition during infection." (PMID 41267684, 2025). "Although the abundance of some lncRNAs with immunomodulatory activity, such as lincRNA-EPS, Lethe, Malat1, and Gas5, does not change significantly at 24 h post-infection, lincRNA-Cox2 (Ptgs2os2) was highly overexpressed in these cells during the Brucella infection." (PMID 38464511, 2024). "Known NMD substrates related to cell stress (Growth Arrest Specific 5, GAS5; transducin beta-like 2, TBL2; and DNA damage-inducible transcript 3, DDIT3) were increased in infected cells, possibly as a result of alterations in the NMD pathway and of a direct effect of the infection." (PMID 36768954, 2023). "Consequently, using INS-1 832/13 rat β-cell line, we found that overexpression of GAS5 by lentivirus infection increased glucose-stimulated insulin secretion and insulin content compared with negative control, whereas knockdown of GAS5 expression reduced both them." (PMID 33195407, 2020). "The results showed that 1 and 6 h post-infection with S2308, RB51, or stimulation with HKBA did not significantly affect the expression of lincRNA-Cox2, Lethe, lincRNA-EPS, GAS5, and Malat1 in RAW264.7 macrophages compared to the unstimulated group." (PMID 38464511, 2024).
neurological disorders (8 papers, 2017 to 2025). "In addition to its detrimental effects in CIS and PD, GAS5 has also been implicated to be involved in the development of other inflammation-related neurological disorders." (PMID 39941145, 2025). "Consistently, the knockdown of GAS5 in the context of the inflammation-related neurological diseases appears to have substantial therapeutic potential." (PMID 39941145, 2025). "GAS5 appears to have a distinctly detrimental role in the context of multiple inflammation-related neurological diseases." (PMID 39941145, 2025). "Although research on the importance of GAS5 in neurological disorders such as AD is scarce, GAS5 levels are significantly higher in patients with AD than controls." (PMID 36671403, 2022). "Taken together, our results showed that GAS5 potentially regulates mitochondrial function, neurological diseases, and synapse function through interacting with specific protein clusters in the mouse brain hippocampus." (PMID 33777096, 2021). "The results revealed that the top global networks modulated by reduction of GAS5 involved changes in hereditary, metabolic, and neurological diseases." (PMID 28035057, 2017). "We thus speculated that GAS5 might play a role in some neurological diseases." (PMID 33777096, 2021).
lung (5 papers, 2019 to 2025).
infectious disease (4 papers, 2018 to 2022). A disorder directly resulting from the presence and activity of a microbial, viral, or parasitic agent in humans. "The lncRNA GAS5, which accumulates in infectious diseases, could function as a potent repressor of the glucocorticoid receptor (GR) and occlude the anti-inflammatory effects of endogenous glucocorticoids." (PMID 35495674, 2022). "GAS5 is important in immune functions and pathogenesis of inflammatory and infectious diseases." (PMID 33240872, 2020).
adenocarcinoma (2 papers, 2015 to 2020). A common cancer characterized by the presence of malignant glandular cells. "In this work, we report, for the first time, that GAS5 downregulation is not only associated with adenocarcinoma tumorigenesis and progression but is also associated with primary resistance to EGFR-TKIs, both in vitro and in vivo." (PMID 25925741, 2015). "Our study shows, for the first time, that the upregulation of GAS5 can overcome the resistance of human adenocarcinoma cells to EGFR-TKIs, at least partially by downregulating IGF-1R." (PMID 25925741, 2015).
bacterial infectious disease (2 papers, 2018 to 2020). An acute infectious disorder that is caused by gram positive or gram negative bacteria; representative examples include pneumococcal, streptococcal, salmonella, and meningeal infections. "GAS5 levels are alerted in virus or bacterial infectious diseases." (PMID 29675399, 2018).
benign tumors (2 papers, 2015 to 2024). "However, GAS5 was almost equally expressed between benign tumors compared with the adjacent normal tissues." (PMID 25925741, 2015). "GAS5 (Growth Arrest-Specific 5) is another lncRNA and its downregulation was observed in TC cell lines and PTC in contrast with samples containing benign tumour." (PMID 39558949, 2024).
digestive system tumors (2 papers, 2019 to 2022). "The discovery of GAS5 and in-depth study of single nucleotide polymorphism (SNP) mechanism can provide a new way for the prevention and treatment of digestive system tumors." (PMID 30606744, 2019). "LncRNA growth arrest-specific 5 (LncRNA GAS5) is a new type of lncRNA that has attracted researchers’ attention recently and plays an important role in the development of tumors, especially in digestive system tumors." (PMID 30606744, 2019). "This article summarizes the expression and mechanism of GAS5 in digestive system tumors." (PMID 30606744, 2019). "The lncRNA growth arrest-specific 5 (GAS5) is a novel lncRNA that has attracted the attention of researchers in recent years and plays an important role in the development of tumors, especially in digestive system tumors." (PMID 30606744, 2019).
heart disease (2 papers, 2022 to 2023). "The lncRNA databases also recommend other heart disease-related lncRNAs, which were differentially expressed in particular ANT-treated conditions, including MALAT1, MEG3, TUG1, GAS5, CASC1S." (PMID 35415316, 2022).
immune diseases (2 papers, 2021 to 2022). "Among well‐known functional lncRNAs, lncRNA growth arrest‐specific 5 (lnc‐GAS5) has been reported to play an important role in regulating the differentiation of T cells in diseases associated with immune dysfunction." (PMID 34473845, 2021). "Regarding GAS5, the lncRNA is involved in several forms of cellular proliferation, cell differentiation, cell transition, immune disorders, and angiogenesis." (PMID 35456391, 2022).
neurodegenerative disease (2 papers, 2023 to 2024). A disorder of the central nervous system characterized by gradual and progressive loss of neural tissue and neurologic function. "In conclusion, we have demonstrated that GAS5 is an important, viable target in neurodegenerative diseases and NPC86 has a tremendous therapeutic potential in the aging process to prevent the advent of neurodegenerative diseases." (PMID 36609440, 2023).
retinopathy (2 papers, 2020 to 2024). "The present study is the first to demonstrate dysregulation of H19 and GAS5 circulating RNAs in diabetic patients with and without retinopathy compared to controls in a population from the Middle East region." (PMID 31999937, 2020).
inflammation (1 paper, 2025). Aberrant reaction of the microcirculation characterized by movement of fluid and leukocytes from the blood into extravascular tissues. "We conclude that there is a ceRNA relationship between GAS5, miR-223-3p, and NLRP3; PAMK alleviates LPS-induced pyroptosis in macrophages through the lncRNA GAS5/miR-223-3p/NLRP3 axis; and PAMK intervention in the macrophage pyroptosis process subsequently alleviates liver inflammation." (PMID 40799819, 2025).